GYG2 (glycogenin 2)
Description:
Glycogenin participates in the glycogen biosynthetic process along with glycogen synthase and glycogen branching enzyme. It catalyzes the formation of a short alpha (1,4)-glucosyl chain covalently attached via a glucose 1-O-tyrosyl linkage to internal tyrosine residues and these chains act as primers for the elongation reaction catalyzed by glycogen synthase.
Synonyms: GN-2; GN2
Tractability: PROTAC: ubiquitination databases record sites on it.
Gene: Protein-coding gene on chromosome X (2,828,571 to 2,890,109, forward strand). Ensembl gene ENSG00000056998.
Subcellular location: Cytoplasm; Nucleus
Subcellular location (Human Protein Atlas): Cytosol; Nucleoli; Centrosome; Mitotic spindle; Nucleoplasm
Pathways (Reactome):
Disease: Glycogen storage disease type 0 (liver GYS2); Glycogen storage disease type IV (GBE1)
Metabolism: Glycogen breakdown (glycogenolysis); Glycogen synthesis
Gene Ontology:
Molecular function: glycogenin glucosyltransferase activity; protein binding; glycosyltransferase activity
Biological process: glycogen biosynthetic process
Cellular component: cytoplasm; cytosol; nucleus
Homologues: Orthologues: chimpanzee GYG2 (99% identical), macaque GYG2 (95% identical), dog GYG2 (73% identical), pig GYG2 (69% identical), tropical clawed frog gyg2 (47% identical), zebrafish gyg2 (40% identical). Paralogues in human: GYG1 (43% identical).
Diseases named in the same sentence as GYG2 in open-access papers:
GYG2 is named in the same sentence as 16 diseases in open-access papers, as found by Europe PMC text mining. Sharing a sentence is not in itself a finding about the gene and the disease. The quoted sentences say what the papers report.
breast carcinoma (1 paper, 2020). "In addition, we identified five ceRNA pairs (i.e., CDH5 with FAM212B, CDH5 with GYG2 in Module 45, TRIB1 with IL33, TRIB1 with INMT, and TRIB1 with MMRN1 in Module 110) that can be used as prognostic markers of breast cancer in BRCA-associated modules." (PMID 32256525, 2020).
cardiomyopathy (1 paper, 2020). A disease of the heart muscle or myocardium proper. "However, nonfunctional glycogenin-1 but not glycogenin-2 was identified in cardiac muscle from patients with cardiomyopathy due to GYG1 missense mutations." (PMID 31628455, 2020).
coronary artery disease (1 paper, 2024). "GYG2 is also an x-linked protein, warranting further testing to examine its role in promoting sex-specific risk of coronary artery disease." (PMID 39796045, 2024).
diabetes (1 paper, 2025). "Although the contribution of GYG2 deletion to diabetes susceptibility remains inconclusive, our data raise the possibility that loss of GYG2 may reduce metabolic flexibility and impair glucose homeostasis, particularly when additional genetic or environmental stressors are present." (PMID 40670355, 2025). "This similarity indicates that GYG2 KO cells may serve as a useful model for studying aspects of the metabolic dysregulation seen in diabetes." (PMID 40670355, 2025). "Although that study did not demonstrate a genetic link between GYG2 deletion and diabetes, the observed co-occurrence in several individuals raises the possibility of a metabolic association that merits further exploration." (PMID 40670355, 2025).
glycogen storage disease (1 paper, 2020). "To check the specificity of the antibody in immunohistochemistry, we studied liver specimens from patients without glycogen storage disease but in whom the biopsy had groups of liver cells with no PAS-positive glycogen, thereby revealing the glycogenin-2 epitopes." (PMID 31628455, 2020).
glycogen storage disease type 0 (1 paper, 2021).
Leigh syndrome (1 paper, 2019). A progressive neurological disease defined by specific neuropathological features associating brainstem and basal ganglia lesions. "Similarly, GYG2 mutation has been characterized as a pathogenic mutation in human Leigh syndrome, an early-onset progressive neurodegenerative disorder resulting from defective glycogen synthesis." (PMID 31831591, 2019).
lung carcinoma (1 paper, 2021). "To identify novel oncogenes, we focused on 21 downregulated genes that have not been extensively investigated for potential association with lung cancer, including PIF1, GYG2, and PGM2L1." (PMID 34608398, 2021).
metabolic disorders (1 paper, 2025). "The involvement of GYG2 in both glycogen structure and mitochondrial activity raises the possibility that GYG2 contributes to metabolic adaptability in energy-storing tissues, and its dysregulation may influence glucose handling in metabolic disorders." (PMID 40670355, 2025).
tumor (1 paper, 2020). "The upregulation of GYG2 expression in the TCGA cohort was also inversely associated with several other prognostic factors including the tumor basal diameter, epithelioid morphology, closed connective tissue loops, and mitotic count." (PMID 32751097, 2020). "Tumors with the largest basal diameter above 13 mm exhibited a decline in BAP1, EPM2A, GYG1, GYG2, and PPP1R3C levels, whereas only EPM2A was negatively associated with an increased tumor thickness." (PMID 32751097, 2020). "However, it is not explored yet, whether the depletion of the glycogenin isoforms GYG1 or GYG2 induces such a glycolytic switch in tumor cells." (PMID 32751097, 2020).
GYG2 also shares sentences with these, for which no sentence is quoted: acute coronary syndrome (1 paper); cancer (1); dementia (1); myopathy (1); Parkinson disease (1); urinary tract infection (1).